CCL4 (C-C motif chemokine ligand 4)
Diseases named in the same sentence as CCL4 in open-access papers (continued):
Sharing a sentence is not in itself a finding about the gene and the disease.
liver fibrosis (continued). "In vivo, inhibiting miR-142-5p and increasing miR-130a-3p expression with locked nucleic acid-modified oligonucleotides inhibits CCL4-induced liver fibrosis and bleomycin-induced lung fibrosis in mice." (PMID 26436920, 2015). "Two models of liver fibrosis (CCL4 and BDL) were established in our experiments, which were identified as successful models of human liver fibrosis." (PMID 24860243, 2014). "Liver fibrosis was induced in a mouse model using CCL4 (intraperitoneal injection, three times a week for 8 weeks), and astaxanthin was administered everyday at three doses (20, 40, and 80 mg/kg)." (PMID 24860243, 2014). "In the present study, we used CCL4 injection and bile duct ligation to induce liver fibrosis in mice and to further investigate the effect of astaxanthin on liver fibrosis and its potential protective mechanisms." (PMID 24860243, 2014). "Previously, we showed that exogenous cytokine IL-10 suppresses liver fibrosis progression induced by CCL4 in rats." (PMID 24993843, 2014). "Our results confirmed this phenomenon as the level of autophagy was upregulated in CCL4-induced liver fibrosis." (PMID 24860243, 2014). "In conclusion, although the pathways about anti-fibrosis property of PZQ are enigmatic, we demonstrated the effects of anti-fibrosis of PZQ in mice with both chronic and advanced schistosomiasis as well as in CCL4-induced liver fibrosis mice." (PMID 21629648, 2011). "In order to confirm the anti-fibrotic properties of praziquantel, we established a CCL4-induced model and revealed that CCL4-induced liver fibrosis was inhibited by PZQ treatment for 30 days." (PMID 21629648, 2011). "The CO6-MMP was significantly related to liver fibrosis in CCL4 treated rats treated for 12–20 weeks." (PMID 21935455, 2011). "Histological examination revealed that the degree of liver fibrosis progressed in mice that received CCL4 relative to mice receiving olive oil alone." (PMID 21283674, 2011). "As expected, PZQ treatment significantly reduced liver collagen areas and hydroxyproline content in mice of CCL4-induced liver fibrosis." (PMID 21629648, 2011). "In order to confirm the anti-fibrotic properties of PZQ, we established mice model of CCL4-induced liver fibrosis." (PMID 21629648, 2011). "In a CCL4-induced mouse liver fibrosis model, we compared the miRNA expression profile from CCL4 and olive oil administrated liver specimens on 4, 6, and 8 weeks." (PMID 21283674, 2011). "Unlike schistosome egg induced hepatic granuloma and fibrosis, CCL4-induced liver fibrosis is mainly due to the damage of hepatocyte." (PMID 21629648, 2011). "We constructed experimental models of hepatic fibrosis involving five stages from F0 to F4 via administration of CCL4 (0.01 ml/kg BW) every 3 days for 3 months." (PMID 17686161, 2007). "What’s more, it has been shown that neuropeptide (NPY) is upregulated in human MASLD and that B cells may require dipeptidyl peptidase 4 (DPP4) to contribute to CCL4-induced hepatic fibrosis via NPY to induce maximal collagen production (Wang XM." (PMID 40761743, 2025). "In the current study, we observed that MSC transplantation could effectively ameliorate liver fibrosis in CCL4-induced mouse model, primarily through sEV-mediated communication with macrophages." (PMID 40873954, 2025). "Indeed, JIB-04, an H3K36me3 agonist, effectively suppressed KC activation by reactivating IL-10 expression and alleviated symptoms of CCL4-induced liver fibrosis." (PMID 40651612, 2025). "Avagacestat also attenuated fibrogenesis in the CCL4‐induced hepatic fibrosis mouse model." (PMID 39665319, 2025). "Both the BDL and CCL4 mice demonstrated liver inflammation and severe hepatic fibrosis." (PMID 39804962, 2025). "However, research indicates that in CCL4-induced mouse models of liver fibrosis, fibrotic liver dendritic cells (FLDCs) exhibit a distinct and mature phenotype compared to normal liver dendritic cells (NLDCs)." (PMID 41488615, 2025).
liver fibrosis (continued). "Combined results in the group treated with BTZ loaded in targeted NPs with VA, indicated a tremendous anti-fibrotic capacity by suppressing HSCs activation and reducing the expression of NF-κB and TGF-β, further ameliorating liver fibrosis in the CCL4-induced mouse model." (PMID 40636301, 2025). "Next, we investigated the therapeutic effects of human Int‐Orgs on CCL4‐induced liver fibrosis." (PMID 40619613, 2025). "Moreover, some of these chemicals induce fibrotic processes, as is the case for rifampin, isoniazid, TAA, and CCL4, demonstrating the role of mitochondrial dysfunction in the pathology of liver fibrosis." (PMID 38676876, 2025). "In a mouse model of liver fibrosis induced by C-C Motif Chemokine Ligand 4 (CCL4), exosomes derived from mesenchymal stem cells (MSCs) carrying miR-26a were shown to promote ferroptosis in hematopoietic stem cells (HSCs) and regulate SLC7A11 expression, thereby alleviating liver fibrosis." (PMID 40191227, 2025). "Notably, we constructed mouse models of liver fibrosis induced by MCD diet or CCL4 to verify the expression changes of characteristic genes as fibrosis progresses." (PMID 40406118, 2025). "CCL4-mediated mouse liver fibrosis model is a commonly used model for studying liver fibrosis." (PMID 40890107, 2025). "In the present study, dramatically elevated inflammation was found in fibrotic liver induced by HCHFD and CCL4, implying that limiting inflammation may represent a prospective approach to prevent deterioration of liver fibrosis in largemouth bass." (PMID 41322258, 2025). "Moreover, region of picrosirius red staining was increased in the CCL4 group compared to the control group, indicating the CCL4-induced development of liver fibrosis." (PMID 38935609, 2024). "Furthermore, we performed gene set enrichment analysis (GSEA) on these major pathways in the CCL4-induced liver fibrosis dataset GSE120281." (PMID 39194690, 2024). "Moreover, the effect of BMSC-derived exosomal miR-26a on liver fibrosis was evaluated in CCL4-induced mice, an in vivo model of liver fibrosis." (PMID 38756248, 2024). "Therefore, we established a CCL4-induced mouse model of hepatic fibrosis and evaluated the effect of KIF18A overexpression on hepatic fibrosis in mice via intravenous injection of adenovirus." (PMID 38372748, 2024). "Moreover, injection of miR-26a mimic-Exo reduced liver fibrosis, and improved the liver function in CCL4-induced mice." (PMID 38756248, 2024). "Previous studies demonstrated that collagen degradation was weakened when Ly-6Clo subgroup macrophages were knocked out in the repair stage of the CCL4-induced liver fibrosis mouse model, which strongly proves that Ly-6Clo subgroup macrophages play a crucial role in degrading liver collagen." (PMID 39635524, 2024). "Using a mouse liver fibrosis model induced by intraperitoneal injection of CCL4, it was observed that oral quercetin treatment resulted in lower portal inflammation scores, decreased serum enzymes ALT and AST, as well as reduced collagen deposition and fibrosis scores." (PMID 39185304, 2024). "In the mouse model of liver fibrosis induced by CCL4, BM-MSCs were injected into the injured liver of mice, which significantly reduced the level of IL-17 and increased the level of IL-10, and alleviated the degree of liver fibrosis." (PMID 36644008, 2023). "Restoring miR-122 expression significantly reduces alcohol and CCL4-induced liver fibrosis." (PMID 38067261, 2023). "Inactivation of NRP1 prevented Ccl4-induced liver fibrosis in vivo." (PMID 36653359, 2023). "In summary, our study suggests that YJSB could significantly protect rats against CCL4-induced hepatic fibrosis by alleviating liver injury and inhibiting the activation of hepatic stellate cells." (PMID 37229248, 2023).
liver fibrosis (continued). "Treatment of a mouse model of CCL4-induced hepatic fibrosis and BM-derived macrophages with hAEC-derived EVs led to an increase in the polarization of the macrophages towards the M2 phenotype and, consequently, a significant reduction in liver fibrosis and macrophage infiltration, respectively." (PMID 37830562, 2023). "Importantly, PPARGC1A-knockout mice challenged with CCL4 or a high-fat diet presented abnormal mitochondrial fission, increased oxidative stress, and more severe liver fibrosis than wild-type mice." (PMID 37296834, 2023). "Estrogen increases the expression of miRNA-29a and decreases CCL4 induction in the liver, which may inhibit hepatic steatosis and hepatic fibrosis." (PMID 38020132, 2023). "In CCL4-induced liver fibrosis, rapamycin has an effective protective effect on the liver." (PMID 36759593, 2023). "For example, we could transplant human liver organoids into immunodeficient animals and induce liver fibrosis with CCL4 or other toxins to establish in vivo human liver fibrosis models for drug tests." (PMID 36864321, 2023). "In addition, the expression of PINK1 and Parkin was significantly reduced in CCL4-induced liver fibrosis mice and Kupffer cell (KC)-transformed HSC cell models." (PMID 38139341, 2023). "Hepatic fibrosis nodules and enlargements of spleens were evidently induced by CCL4 in model mice, however both HFFs and UC-MSCs treatments could markedly blunt the CCL4-induced hepatic fibrosis nodules and enlarged spleens." (PMID 35831878, 2022). "In CCL4-induced liver fibrosis, ET-1 expression was increased, suggesting that ET-1 could be a promising marker." (PMID 35529927, 2022). "GZFL could inhibit acetaldehyde‐induced cellular fibrosis and alleviate CCL4‐induced liver fibrosis by inhibiting TGF-β1/Smad2/3, CUGBP1 signaling and activating IFN-γ/STAT1/Smad7 signaling." (PMID 35387552, 2022). "Additionally, systemic administration of CXCL9 prevented the development of CCL4 induced liver fibrosis in a murine model." (PMID 35194136, 2022). "Vildagliptin modulates ERK1/2, p38α and NF-κB signaling to reduce CCL4-induced liver fibrosis." (PMID 36267567, 2022). "The findings demonstrated that the CCL4-induced rat hepatic fibrosis model was effectively created." (PMID 36017390, 2022). "Moreover, both protein and mRNA level of SYK in HSCs and hepatocytes is positively correlated with α-SMA (the maker of liver fibrosis) in liver biopsies from patients and CCL4-induced mice liver fibrosis model." (PMID 36568669, 2022). "Importantly, injection of NEAT1-depleted exosomes attenuated the CCL4-induced liver fibrosis and mitigated the AST and ALT levels as well as pro-fibrotic makers, including collagen I and α-SMA." (PMID 35585044, 2022). "In addition to the acute CCL4 liver fibrosis model, we also found that liver fibrosis was significantly attenuated after TMAO treatment in the NASH model, as determined by H&E, Sirius red, Masson staining and Western blot of αSMA." (PMID 36072588, 2022). "HFFs treatment could equivalently alleviate above CCL4-induced indicators of liver fibrosis, like the UC-MSCs treatment." (PMID 35831878, 2022). "In the CCL4-induced mouse liver fibrosis group, HBO1 knockdown inhibited the production of ROS." (PMID 36524217, 2022). "In contrast, administration of PAs into CCl4-induced rats’ hepatic fibrosis produced a significant reduction in DNA damage, as evidenced by a significant (P < 0.05) decrease in the values of these parameters, compared with the CCL4-treated rats." (PMID 35881285, 2022). "In addition, administration of PAs in rats with CCl4-induced liver fibrosis resulted in a significant (P < 0.05) improvement in the levels of these biomarkers in serum compared with the CCL4-treated rats." (PMID 35881285, 2022). "Previous studies suggested that HFFs could propel fibrosis, but our study verified that HFFs had the same therapeutic capacity in CCL4-induced liver fibrosis as UC-MSCs." (PMID 35831878, 2022).
liver fibrosis (continued). "In addition, UC-MSCs and fibroblasts had nearly equal therapeutic efficacy on TNBS-induced colitis and CCL4-induced hepatic fibrosis." (PMID 35831878, 2022). "Conversely, in hepatocyte-specific HIF-1α deficient mice when only CCL4 treatment was given, liver fibrosis did not reduce." (PMID 36523459, 2022). "Furthermore, morin has been reported to upregulate nuclear factor erythroid 2-related factor 2 (Nrf2) and hemeoxygenase-1, thereby decreasing oxidative stress in the liver and CCL4-induced hepatic fibrosis." (PMID 35624827, 2022). "In the liver, the deletion of SOX9 in vivo has been shown to attenuate CCL4-induced liver fibrosis." (PMID 34520400, 2021). "Furthermore, miR-497 inhibitor delivered by highly-hepatotropic (rAAV8) inhibited TGF-β/smads signaling pathway by targeting at Smad7 to ameliorate CCL4-induced liver fibrosis." (PMID 34521449, 2021). "To investigate whether TIM‐4 interference in KCs can reverse CCL4‐induced liver fibrosis, we administered TIM‐4 mAb (0.35 mg/mouse, once per week, for six weeks, red fluorescence labelled) via caudal vein injection to block the function of TIM‐4 in KCs." (PMID 31755616, 2020). "It was verified that TIM‐4 interference could essentially decrease the hydroxyproline and collagen deposition in CCL4‐induced liver fibrosis." (PMID 31755616, 2020). "Elafibranor attenuated fibrosis in the CCL4-induced liver fibrosis model." (PMID 33343375, 2020). "TIM‐4 was demonstrated to be present in KCs at high levels in CCL4‐induced liver fibrosis." (PMID 31755616, 2020). "And overexpression of GCLC in vivo could significantly decrease collagens in CCL4-induced and pig serum-induced liver fibrosis model." (PMID 33015132, 2020). "In vivo Hic-5 knockdown, even after induction of liver fibrosis by CCL4, could improve the progression of pathology." (PMID 33154390, 2020). "To test whether this intestinal-AP is able to attenuate liver fibrogenesis, we administered exogenous intestinal AP into the circulation of mice with CCL4-induced liver fibrosis." (PMID 33348845, 2020). "In a model of reversible CCL4-induced liver fibrosis similar to the one used here, gene expression profiling has been done on liver infiltrating CX3CR1+ Ly6Chi monocytes at the necro-inflammatory phase (24 h) and their MoMF progenies at the early resolution phase (72 h)." (PMID 32296422, 2020). "We now examined whether this activity is also increased in CCL4-induced liver fibrosis in mice and in human cirrhotic patients." (PMID 33348845, 2020). "The effects of intestinal AP were studied in mice with CCL4-induced liver fibrosis." (PMID 33348845, 2020). "A previous study suggested that CD8 T cells (Ccl5+, Ccl4+) might promote liver fibrosis via extrahepatic recruitment in response to liver injury." (PMID 33391261, 2020). "Sal B also inhibited CCL4-induced liver fibrosis by the NF-Kb/IκBα signaling pathway." (PMID 30842735, 2019). "MSCs were obtained from 10 male Sprague-Dawley rats while 50 female rats were divided into control (CG), liver fibrosis (CCL4, intraperitoneal injection of CCl4 for 8 weeks), and CCL4 rats treated with SPIO-labeled MSCs (MSCs/CCl4) with and without continuing CCL4 injection for another 8 weeks." (PMID 31781620, 2019). "To investigate whether the increased liver fibrosis induced by BDL or CCl-4 was paralleled by HSC activation, we determined α-SMA expression using immunofluorescence and RT-PCR on livers from the three groups." (PMID 30875826, 2019). "Furthermore, other CCRs such as CCR1 and CCR5, via CCL3/MIP1α, CCL4/MIP1β and CCL5/RANTES interaction have been implicated in liver fibrosis attributed to Ly-6Chigh monocytes recruitment or stellate cells activation, respectively." (PMID 31849997, 2019). "Together, these data demonstrate that CDH11-/- mice have decreased liver fibrosis induced by CCL4." (PMID 31269038, 2019). "PAR-2 deficiency, using PAR-2 knockout mice, has been shown to reduce CCL4 induced liver fibrosis." (PMID 29739329, 2018).
liver fibrosis (continued). "Using FACS, we isolated Lgr5-GFP+ liver stem cells from Lgr5-GFP mice treated with 1XCCL4, and injected these cells intrasplenically into the wild-type C57 mice with acute liver damage (single CCL4 treatment) or chronic liver damage (liver fibrosis model, 2XCCL4 treatment/week for 6 weeks)." (PMID 29079780, 2017). "Next, we detected whether Lgr5+ liver stem cells were maintained upon chronic damage during CCL4-induced liver fibrosis development." (PMID 29079780, 2017). "In CCL4-induced mice liver fibrosis, ET-1 gene expression is increased." (PMID 28770223, 2017). "Hence, the requirement for a CCL4 induced liver fibrosis is inevitable to investigate such a complicated disease to save many lives in the world and in this study we presented an efficient protocol to have fibrotic liver rat models in Sprague Dawley strains." (PMID 29511482, 2017). "To verify whether rHGF/rRspo1 recovers the liver functions through Lgr5+ liver stem cells induction, we knocked down Lgr5 expression using Ad-Lgr5 shRNA infection in the CCL4-induced liver fibrosis model." (PMID 29079780, 2017). "Furthermore, ectopic expression of miR-101, which is down-regulated in activated HSCs, greatly reduced CCL4-induced hepatic fibrosis and miR-101 inhibitor showed an opposite effect with increased fibrogenesis." (PMID 26999230, 2016). "Similarly, miR-17-5p, a regulator of TGF-β/Smad pathway, was up-regulated in CCL4-induced hepatic fibrosis models in mice and was also elevated in serum of patients with cirrhosis compared to healthy controls." (PMID 26999230, 2016). "In addition, to determine the therapeutic effect of fraxinellone on liver fibrosis, we administered fraxinellone in mice five weeks or three weeks after the CCL4 treatment and found that fraxinellone was able to inhibit the progression of established fibrosis." (PMID 27853137, 2016). "Furthermore, a recent study indicates that bee venom inhibits CCL4-induced hepatic fibrosis through suppression of fibrogenic cytokines in liver fibrosis animal model." (PMID 26580653, 2015). "However, transferring either monocytes or M(IL-13) into the Ccr2−/− mice recapitulated hepatic fibrosis, with M(IL-13) transfer at a later stage (between 3 to 5 weeks following the CCL4 challenge) showing the most prominent profibrogenic effects." (PMID 26436920, 2015). "In addition, miR-199a-5p was significantly decreased during regression of experimental CCL4-induced liver fibrosis." (PMID 23459460, 2013). "Also, S. tetrandra S. Moore reduced the levels of serum GOT and GPT in the rat cirrhosis model induced by CCL4, and it was effective in reducing hepatic fibrosis and nodular formation." (PMID 18475741, 1996). "Furthermore, a CCL4-induced liver fibrosis model was established and treated with JIB-04." (PMID 40651612, 2025). "In addition, in the CCL4 mouse model of liver fibrosis, it was found that HSCs could expressed IL-22 receptor 1 in large quantities." (PMID 39995661, 2025). "Consequently, we constructed a CCL4-induced mouse liver fibrosis model." (PMID 40406118, 2025). "Notably, in the untreated group, the protein expression levels of pro-fibrotic mediators TGF-β, p-Smad2, and p-Smad3 were markedly elevated compared with the healthy group in the CCL4‐induced liver fibrosis model, consistent with the hyperactivation of this pathway during fibrosis progression." (PMID 40483470, 2025). "Although DMDD has been shown to be effective in various disease mouse models, to understand whether DMDD can alleviate liver fibrosis, we adopted the most commonly used CCL4-induced method to construct a mouse model of liver fibrosis while applying DMDD for treatment." (PMID 40453659, 2025). "In addition, miR-214 is deeply involved in liver fibrosis by targeting and regulating the expression of fused homolog protein suppressor, and the knockdown of miR-214 alleviates liver fibrosis in carbon tetrachloride (CCL4)-treated mice." (PMID 37833930, 2023).